BRD3 (bromodomain containing 3)
Diseases named in the same sentence as BRD3 in open-access papers (continued):
Sharing a sentence is not in itself a finding about the gene and the disease.
cancer (53 papers, 2011 to 2025). A tumor composed of atypical neoplastic, often pleomorphic cells that invade other tissues. "The elevated expression of BRD2/BRD3/BRD4/YAP1 is a risk factor from the Cox cross-pan-cancer dataset proportional hazards model in a variety of tumors, including SKCM, besides, there was an association between BRD4 and YAP1." (PMID 38169595, 2024). "The mammalian bromodomain and extra-terminal domain (BET) family of proteins consists of four conserved members (Brd2, Brd3, Brd4, and Brdt) that regulate numerous cancer-related and immunity-associated genes." (PMID 37049806, 2023). "Our results found that higher mRNA and protein expressions of BRD3 were found in HCC, and mRNA expression of BRD3 was remarkably linked with cancer stages and tumor grades." (PMID 32927435, 2020). "Furthermore, Brd3 is a member of the bromodomain-containing protein family associated with wide-range activation of super-enhancers in cancer." (PMID 25517911, 2014). "Small-molecule BETi targeting of the epigenetic reader BRD–containing proteins BRD2, BRD3, and BRD4 has been developed to cause cancer cell death." (PMID 40632844, 2025). "According to the preliminary pharmacophore-based screening, kaempferol, and withanolides D and O were suggested to bind with both CDK2 and BRD3, respectively, as cancer-relevant target proteins." (PMID 38303989, 2024). "A PPI network analysis was used to identify 17 potential targets of saponins aglycone in cancer cells, and the binding modes of saponins aglycone to four of these targets (BRD3, GLO1, CDK6, and HRAS) were confirmed using docking and MD simulations." (PMID 37996449, 2023). "On the other hand, among the four BET family of proteins, Brd4 has been the most extensively studied, whereas the relative role of Brd2/Brd3 in cancer cell survival still remain elusive." (PMID 37049806, 2023). "Taken together, these data indicate that BRD3 plays a compensatory function in phase separation in cancer cells using ZXH-3-26." (PMID 37156794, 2023). "We first compared the expression levels of BRD2, BRD3, and BRD4 in ACC patients with different cancer stages and found that BRD3 and BRD4 transcript levels were significantly upregulated in patients with ACC." (PMID 36793283, 2023). "We first compared the expression levels of BRD2, BRD3, and BRD4 in ACC patients with different cancer stages and found that the BRD3 (stage 4) and BRD4 transcript levels were significantly upregulated in patients with ACC (P < 0.05)." (PMID 36793283, 2023). "Taken together, these results suggest that BRD3 plays important roles in cancer cell growth and migration." (PMID 34605158, 2022). "Intriguingly, we found two bromodomain containing proteins (BRD2 and BRD3) noted to be relevant in cancer interacting with MALAT1." (PMID 32050583, 2020). "Mining a large dataset of pooled CRISPR screens in cancer cell lines further supported an anti-proliferative role for BRD3." (PMID 30554943, 2019). "The object of this study were three of the four BET proteins BRD2, BRD3 and BRD4 and to our knowledge, this is the first spectroscopic characterization in solution of human BRDs variants found in cancer." (PMID 27403962, 2016). "The involvement of BRD3 in cancer showed its role in the certain NMC translocations, and BRD3 can potentially associated with MLL fusion oncoproteins in leukemogenesis." (PMID 25849938, 2015). "To explore the potential role of BRD3, we first examined BRD3 mRNA expression in cancer cell lines." (PMID 34605158, 2022). "We also found that BRD3 silencing decreased the proliferation and migration of cancer cells." (PMID 34605158, 2022). "Nevertheless, further research is required to determine whether the BRD3 abnormalities themselves affect cancer prognosis or whether they affect cancer prognosis through the interactions of other epigenetic modulators and/or oncogenes." (PMID 34605158, 2022).
cancer (continued). "However, most previous studies of BETi mainly examined BRD2/BRD3/BRD4 proteins in cancer cells; few studies have considered the effects of BETi on macrophages." (PMID 35094142, 2022). "BRD3 may affect cancer prognosis by controlling the expression of oncogenes, such as MYC, in a similar manner to BRD4." (PMID 34605158, 2022). "While BRD4 is the most studied among BET proteins, there are several reports indicating that BRD2 and BRD3 might also play an important role in dysregulating oncogenes in cancer." (PMID 34440844, 2021). "The protein with UniProt ID Q15059 is bromodomain-containing protein 3 (BRD3), a member of the bromodomain and extra-terminal motif (BET) family that recognizes acetylated lysine residues on histones and regulates transcriptional programs linked to cancer and inflammation." (PMID 41341719, 2025). "The BET family is composed by BRD2, BRD3, BRD4, and BRDT, and plays important roles in cancer by directly regulating the expression of cancer-related genes such as MYC, and the transcription factor NF-κB." (PMID 41551874, 2025). "Bromodomain and outdomain (BET) proteins, mainly composed of BRD2, BRD3, and BRD4 proteins, function as epigenetic readers and transcription coactivators and are currently recognized as therapeutic cancer targets." (PMID 41049615, 2025). "Although we focused on RBM15 and serine metabolism in this study, network analysis revealed that the relationship between RBM15 and other genes with oncogenic potential (CDC42, CDC14B, STK40, BRD3, CPNE1, and MCM3) is also crucial for cancer cell survival." (PMID 38825643, 2024). "Pharmacophore-based inverse virtual screening proposed that BRD3 and CDK2 are the cancer-relevant targets for the annotated withanolides D and O, and the flavonoid kaempferol." (PMID 38303989, 2024). "BRD1, BRD2, BRD3, BRD4, and BRD7-9 were significantly upregulated in tumor samples expressing high levels of p16, a surrogate biomarker for HPV-positive cancers, and the presence of HPV DNA through in situ hybridization, compared to normal samples (p<0.05)." (PMID 39301555, 2024). "BET proteins (BRD2, BRD3, BRD4 and BRDT) serve as the readers of DNA acetylation and regulate the expression of key genes in cancer." (PMID 38893083, 2024). "We subsequently investigated the correlations between the CNV of ISCA1 and the RNA expression of FRGs and reported that the ISCA1 CNV was positively correlated with TSC1, FXN, BRD3, and MAPKAP1 in most cancer types." (PMID 39766805, 2024). "Bromodomain and extracellular terminal (BET) family (including BRD2, BRD3, and BRD4) is considered to be a major driver of cancer cell growth and a new target for cancer therapy." (PMID 36793283, 2023). "The transcriptional levels of BET (BRD1,BRD2,BRD3, BRD4 and BRDT) were compared between cancer and normal samples in GEPIA database." (PMID 36711038, 2023). "We used the Genomics of Drug Sensitivity in Cancer database to evaluate the inhibitory effect of BRD4-targeted drug PFI-1 and (BRD2, BRD3, and BRD4)-targeted drug I-BET-151 on ACC cell lines." (PMID 36793283, 2023). "The expression levels of BRD3 and BRD4 were significantly upregulated in ACC patients at different cancer stages." (PMID 36793283, 2023). "The BET protein family, including BRD2, BRD3, and BRD4, play an important role in cancer, among which BRD4 protein is involved in regulating cancer and inflammatory processes." (PMID 34943817, 2021). "Although various BET inhibitors are undergoing clinical trials for the treatment of cancer and inflammatory diseases, it has to be noted that BET inhibitors target all BET family proteins, including Brd2, Brd3, and Brd4." (PMID 33830083, 2021). "Recognition of the importance of BRD4 in cancer has led to the development of a new generation of anti-cancer compounds that specifically target the BET (bromodomain and extra-terminal motif) family of proteins, of which BRD3 and BRD4 are key members." (PMID 29348827, 2017).
cancer (continued). "The inhibition of BRD2, BRD3, and BRD4 shortens signaling between super-enhancer regions and oncogene target promoters, resulting in cell-specific inhibition of oncogene expression and ultimately cancer cell death." (PMID 36793283, 2023). "In vitro cell studies showed that knockdown of the BRD3/4-NUT gene by siRNA in NC cell lines induced rapid squamous differentiation and arrested growth, which suggested that the BRD3/4-NUT fusion protein blocked differentiation and promoted proliferation of carcinoma cells." (PMID 31815119, 2019). "Therefore, BRD2, BRD3, and BRD4 may be biomarkers for some cancers, and the development of their inhibitors may be a potential strategy for cancer treatment." (PMID 36793283, 2023). "Moreover, because JQ1 also inhibits BRD2, BRD3, and other BET family members, in the future it will be important to test the extent to which BET family members contribute to JQ1 anti-tumor activity in HCC and other cancers." (PMID 26575167, 2016). "Finally, it is worth noting that diverse types of cancer cells are “addicted” to high BRD4 levels to maintain a pro-proliferative transcriptional program, which could negatively impact the expression levels of BRD2 and BRD3, which in the case of BRD3 could contribute to increased proliferation." (PMID 30554943, 2019).
tumor (27 papers, 2016 to 2025). "BRD3 exhibits context-dependent activity: in some tumors it promotes metastasis and tumor progression, whereas in others it has tumor-suppressive effects, positively correlating with p21 expression." (PMID 41583469, 2025). "Another recently developed CRBN-based PROTAC dBET1 has also shown very potent activity in degrading BRD2, BRD3, and BRD4 proteins in association with a potent anti-tumor activity in various AML cell lines." (PMID 36909156, 2023). "Sinonasal NC presents typical undifferentiated or poorly differentiated cells, abrupt keratinization features and heterogeneous genotypes, including BRD4::NUTM1 and BRD3::NUTM1 fusions, with low tumor mutation burden and stable microsatellites." (PMID 38239638, 2023). "In conclusion, sinonasal NC presents typical undifferentiated or poorly differentiated cells, abrupt keratinization features and heterogeneous genotypes, including BRD4::NUTM1 and BRD3::NUTM1 fusions, with low tumor mutation burden and stable microsatellites." (PMID 38239638, 2023). "The majority of these cases manifested a tumor with chromosomal translocation, which forms the BRD4-NUT fusion oncogene (n = 16), BRD3-NUT (n = 4), NSD3-NUT (n = 3), NUT-variant (n = 1), CHRM5-NUTM1 (n = 1) and other NUTM1 rearrangements (n = 5)." (PMID 36290813, 2022). "Therefore, further studies comparing genomically profiled NC tumor cell lines with BRD3, NSD3, or other gene fusion characteristics are needed." (PMID 35681742, 2022). "Notably, the responding patients with NC had tumours harbouring BRD3-NUT and NSD3-NUT fusions, respectively." (PMID 33311588, 2021). "A very recent study in AML reported a highly promising PROTAC compound MZ1, which targets and efficiently degrades BRD2, BRD3, and BRD4 proteins in various AML cell lines, and markedly suppress tumor growth in a xenograft mouse model." (PMID 36909156, 2023). "The results indicated that the expression levels of BRD2, BRD3, BRD4 were higher in GBM tumor tissues than those in normal tissues, and BRDT expression in tumor was lower than that in normal tissues." (PMID 36711038, 2023). "Western blotting showed that BETd-260 treatment completely depleted BRD2, BRD3, and BRD4 proteins in the tumor tissue." (PMID 31653826, 2019). "The results showed that treatment with a single dose (5 mg/kg) of BETd-260 for 24 h significantly suppressed the expression of BRD2, BRD3 and BRD4 in tumor tissue of both HCC models." (PMID 31993368, 2019). "The mRNA levels of BRD3 and BRD4 were significantly higher in primary of tumor (TP) versus normal tissue (NT), while there was no significant change of BRD2 mRNA levels in NT vs. TP." (PMID 29434197, 2018). "Interestingly, genes with oncogenic potential, including CDC42, CDC14B, STK40, BRD3, CPNE1, and MCM3, were downregulated, whereas tumor inhibitors, including CDKN2C, CASP7, and CDKN1B, were upregulated by RBM15 depletion." (PMID 38825643, 2024). "His tumour was positive for NUT expression by IHC and was found to harbour BRD3-NUT rearrangement." (PMID 33311588, 2021). "It is also specific for the VAV2 locus, because the two genes that flank the VAV2 gene (SARDH, BRD3) do not show any consistent variation in expression in the human and mouse tumor datasets interrogated in this study." (PMID 32963234, 2020).
metabolic disorders (1 paper, 2024). "NEAT1 exacerbates metabolic disorders in PCOS mice by downregulating miR-324-3p and upregulating BRD3." (PMID 39334761, 2024).
BRD3 also shares sentences with these, for which no sentence is quoted: infection (11 papers); ACTHomas (1); adenocarcinoma (1); astrocytomas (1); bone cancer (1); botulism (1); chronic myeloid leukemia (1); Cornelia de Lange syndrome (1); cutaneous melanoma (1); enteritis (1); hepatoma (1); Listeria infection (1); malignant pleural mesothelioma (1); oesophageal cancer (1); osteosarcoma (1); ovarian clear cell cancer (1); Paralysis (1); renal fibrosis (1); rhabdomyosarcoma (1); rheumatoid arthritis (1); Sepsis (1); serous ovarian carcinoma (1); stomach cancer (1).